TNF (tumor necrosis factor)
Diseases named in the same sentence as TNF in open-access papers (continued):
Sharing a sentence is not in itself a finding about the gene and the disease.
infection (continued). "At the higher inoculum, WT and tlr4 mutant mice exhibited significantly increased levels of IL-1α, IFN-γ, TNF-α, MCP-1, IL-1β, IL-6, and IL-17A early during infection relative to the lower inoculum while levels dissipated by 7 dpi, consistent with bacterial clearance." (PMID 40817088, 2025). "This is evidenced by normal counts of blood cells and platelets, a lack of pro-inflammatory cell recruitment at the infection site, and minimal serum levels of cytokines such as IL-1β, TNF-α, IL-10, and IL-6." (PMID 40606156, 2025). "Besides analyzing ferroptosis-related protein markers, this cohort study also evaluated traditional biochemical indicators of infection, including IL-1β, IL-6, IL-8, IL-10, CXCL2, and TNF-α." (PMID 40264754, 2025). "The cytokines and chemokines TNF-α and CCL20, which play critical roles in inflammation and immune cell recruitment, were unregulated following infection with all Phialophora species, demonstrating that these pathogens elicit an inflammatory response from the host immune system." (PMID 40727705, 2025). "When the gEVs were vaginally exposed in mice without Ov, they significantly induced RANK, RANKL, and TNF-α expression and NF-κB+ cell numbers in the vagina, femur, hypothalamus, and hippocampus, as observed in GV infection." (PMID 40284791, 2025). "Interleukin-1β (IL1B), interleukin-6 (IL6), tumor necrosis factor (TNF), and interferon-β (IFNB1), as key components of this response, have important functions in initial detection of Mtb, controlling infection, initiating effective T cell responses, and modulating immunopathology." (PMID 40402573, 2025). "The rationale behind this comparison is that TNFα, which is frequently secreted by macrophages or infected cells, binds to TNF receptors on nearby cells, thereby activating an immune response and preparing these cells to defend against potential infections." (PMID 40103806, 2025). "CHIKV infected cells showed no increase in NF-κB activation up to 8 h post infection, behaviour which was indistinguishable from that of the negative control (mock-infected in the absence of TNF-α)." (PMID 40006946, 2025). "Deletion of MGF110-1L, -5L, and -6L in the ASFV genome has been reported to result in increased transcription of multiple host cytokine genes including IFN-α, TNF-α, and IL-12 during genotype II ASFV infection in vitro, but the reasons for this are unknown." (PMID 41156603, 2025). "Concomitantly, genes involved in inflammatory and interferon-related responses, including IFN-γ, IL-12b, STAT1, STAT3, IL-6, TNF-α, CXCL9, CXCL10, and CXCL5, were significantly upregulated, indicating a strong pro-inflammatory environment during peak infection." (PMID 40630939, 2025). "TNF-α, along with reactive nitrogen intermediates (RNI) and reactive oxygen intermediates (ROI), are trypanocidal factors produced by macrophages, which are activated by the presence of IFN-γ to fight infection." (PMID 40743218, 2025). "In this context, the present study aims to compare IL-10, IL-2, IL-6, IL-8, and TNF-α levels between patients with and without HAdV-36 infection." (PMID 40284995, 2025). "While not viewed as classical immune cells, upon infection or other injury, they orchestrate immune activation through the secretion of various pro-inflammatory cytokines (e.g., TNF-α and IL-6) and chemokines (e.g., MCP-1)." (PMID 40278266, 2025). "In addition, 25–100 mg/kg baicalin reduced the mRNA expression levels of IL-1β, IL-6, IL-8, IL-18, TNF-α, and COX-2 in the spleen compared to the infection group (p < 0.05)." (PMID 40427533, 2025). "Compared with Mtb‐infected control macrophages, the level of IL1β was significantly reduced in both HIF1‐KD and GBP1‐KD cells after infection with HN878 or CDC1551, while TNFα and IL6 were significantly reduced only in HN878‐infected HIF1‐KD and GBP1‐KD macrophages." (PMID 41287823, 2025).
infection (continued). "Furthermore, infection led to an increase in the expression of cancer progression-related chemokines Ccl5 and Cxcl16, being upregulated most prominently by SFV/TNFα and SFV/IFNγ." (PMID 40547518, 2025). "To investigate whether RBMX2 mediates intracellular inflammation by regulating the tightness of the epithelial barrier, we measured the mRNA levels of inflammatory factors (IL-1β, TNF, and IL-6) in RBMX2 knockout EBL cells post-infection." (PMID 41277807, 2025). "Enteritidis CMCC50041 infection increased the transcript levels of the intracellular cytokines IL-8 and TNF-α but not as well on those of IL-6 and INF-γ." (PMID 39927265, 2025). "However, the secretion of TNF-α, IL-6, and CXCL-8/IL-8 by DENV-2-infected MDMs occurred at late stages of infection, suggesting that the translation and/or secretion of these inflammatory factors are delayed in DENV-2 replicative cycle." (PMID 40934228, 2025). "It is interesting that the pulmonary IL-6 level, but not the IL-1β or TNFα levels, significantly decreased in mice deficient in caspase-11 or NLRP3 upon infection." (PMID 40034692, 2025). "There was a pronounced effect of ethanol, but not infection, on the increase in the numberof TNF-positive cells in the hippocampus andespecially in the cortex." (PMID 40144377, 2025). "In addition, the ΔrfbBΔrffG strain induced lesser amounts of pro-inflammatory cytokines such as TNF-α, IL6, and IFN-γ than the WT strain in both the oral and the i.p. modes of infection." (PMID 40469742, 2025). "Stimulation of both primary monocytes and THP-1 reporter cell lines with SARS-CoV-2-derived ssRNA led to profound upregulation of all measured cytokine genes, while primary monocytes increased TNF, IL1B and IL6 and decreased CXCL8 expression upon infection with replication-competent SARS-CoV-2." (PMID 39963132, 2025). "Priming with TNFα led to slightly enhanced infection levels and IL-1β secretion in the absence of Vpx-VLPs." (PMID 40920844, 2025). "Up to 3 days post-infection, cell death induced by TNFα, but not by STS, is efficiently blocked, as assessed by PARP cleavage." (PMID 41204030, 2025). "We excluded TNF priming because prolonged TNF treatment (> 10 h) in CMT-93 cells triggered spontaneous caspase-3/7 activity in the absence of infection (Fig. EV3E)." (PMID 40128366, 2025). "In the case of MHV-JHM infection, changes in expression (from 0% to 100%) were visible in IL-6, IL-18, IL-33, ENA-78 (CXCL5), GRO alpha (CXCL1), IP-10 (CXCL10), MCP-1 (CCL2), MIP-1 beta (CCL4), MIP-2 alpha (CXCL2), RANTES (CCL5), and TNF alpha." (PMID 40358160, 2025). "However, the expression of IDO1 in the IDO+ TNF+ ISG subcluster was pustule-specific, suggesting that active IFN-γ-dependent signaling occurred during infection." (PMID 39882906, 2025). "Therefore, the levels of TNF-α, IL-6, IFN-γ, and CCL4 in serum were measured at 4, 24, and 48 h post infection." (PMID 40872776, 2025). "Infection of monocytic THP-1 cells with CFT073ΔtcpC + pASK-IBA5plus-TcpC, which was induced with increasing Atc concentrations, revealed that IL-1β and to a lower extent TNFα secretion was significantly and dose-dependently augmented." (PMID 41310197, 2025). "However, in our study, in the high-dose infection group, elevated STAT1 and ISG expression were accompanied by a marked upregulation of pro-inflammatory cytokines, including IL-6 and TNF-α." (PMID 40941331, 2025). "In experimental infections with T. vivax in cattle and buffalo, a high presence of IFN-γ and TNF-α has been demonstrated, while in natural infections of cattle with T. vivax, the presence of IL-10 has also been detected, in addition to TNF-α." (PMID 40743218, 2025). "IL-4, IL-10, and TNF remained below the detection limit in all experimental groups, regardless of infection status (data not shown)." (PMID 41415569, 2025).
infection (continued). "Myeloid cell-derived TNF regulates bacterial growth, inflammation, and immune cell recruitment into the lungs during early infection but is not required for granuloma organization." (PMID 40427602, 2025). "Moreover, there were significant differences in TNF-α, IL-6, and IFN-γ levels among patients with mild, moderate, and severe infections (P<0.05)." (PMID 40677522, 2025). "TNF-α and IL-1β activate the canonical NF-κB pathway in endothelial cells (ECs), thereby stimulating the production of cell adhesion molecules, such as E-selectin and ICAM-1, which facilitate neutrophil transmigration to sites of infection or injury." (PMID 40562870, 2025). "The results showed that, during PRV (MOI = 0.4) infection, compared to the empty vector group, all METTL3 groups (METTL3, METTL3-S43A, METTL3-S50A, and METTL3-S525A) significantly enhanced the mRNA transcription levels of IL-1β, IL-8, IL-6 and TNF-α." (PMID 40802811, 2025). "Quantitative RT-PCR analyses revealed peak expression levels of pro-inflammatory mediators such as TNF-α and CXCL2 in immune organs; however, CXCL2 expression in the spleen exhibited a slight decline during the late phase of severe infection, possibly reflecting viral immune evasion strategies." (PMID 41009378, 2025). "Moreover, infection with SFV/IFNγ and SFV/TNFα upregulated the amount of IL-6, CCL4 and CXCL11 (p < 0.05)." (PMID 40547518, 2025). "TNF-α levels were significantly reduced in SL-infected C1 cells following Mdivi−1 treatment but did not decrease further in E1 cells after infection." (PMID 41250600, 2025). "Both infection and vaccination elicit robust Th1/Th17-dominant immune responses and increased cytokine production (IL-6, IFN-γ, TNF-α), which may intensify orbital inflammation, despite similar TRAb positivity rates." (PMID 41509944, 2025). "Additionally, a mouse infection model was established using P. aeruginosa PAO1 to investigate the impact of RmmLII on the production of inflammatory cytokines IL-1β, IL-6, and TNF-α, as well as mouse survival rates." (PMID 40170927, 2025). "LAP inhibition did not affect proinflammatory cytokine secretion as the levels of IL-1β, TNF and IL-6 were not affected 24 hours post-infection of macrophages pretreated with SAR405 and GSK2795039, respectively." (PMID 40395986, 2025). "Tumor necrosis factor (TNF-α) is a pivotal proinflammatory cytokine essential for both innate and adaptive immunity, as it activates various immune cells and stimulates the release of additional cytokines to facilitate infection clearance." (PMID 40723325, 2025). "In recent years, the use of biological agents, such as anti-interleukin (IL)-17, anti-IL-23, and anti-tumor necrosis factor (TNF)-α, has demonstrated considerable success in treating patients with severe PSO; however, these agents can induce adverse events (AEs), such as infection." (PMID 39995941, 2025). "However, WT BMDMs exposed to T. gondii in the presence of TNF-α and Z-VAD-FMK showed significant disruption of cell membrane integrity as early as 8 hours post-infection when data are normalized to phase area confluency." (PMID 41055414, 2025). "Cytochalasin D, bafilomycin A1, and chymostatin did not affect TNF secretion from BMDM in response to infection with L. interrogans." (PMID 40501870, 2025). "Gene expression of TNFα in the immunosuppressed mice did not change significantly between days post-infection." (PMID 40586570, 2025). "(A) Confocal images of E-selectin staining in the Vessel-on-Chip (VoC) for four conditions: without infection nor treatment, after 4 hr of either TNFα treatment or infection with wild-type (WT) or pilD Nm strains." (PMID 41406015, 2025). "Furthermore, ROC curve analysis demonstrated that serum TNF-α, IL-6, and IFN-γ levels have good predictive value for DFI infection severity and prognosis, and their combined detection further improves predictive accuracy." (PMID 40677522, 2025).
infection (continued). "An adaptive response driven by T-helper 1 lymphocytes (Th1) triggers an effective immune reaction that helps manage the infection by promoting the production of proinflammatory cytokines such as interferon-gamma (IFN-γ), interleukin-2 (IL-2), and tumor necrosis factor-alpha (TNF-α)." (PMID 41310729, 2025). "However, comparable levels of TNF, IL-6, IL-10, CXCL1, CCL3, GM-CSF, and G-CSF were observed upon CRWT and CRM12 infection." (PMID 40599135, 2025). "Western blot results demonstrated that in IBV-infected CEK cells, baicalin significantly promoted the protein expression of IL-1β, IL-6, TNF-α, TLR7, and MyD88 at 24 h post-infection (hpi), whereas it markedly suppressed the expression of these factors at 48 hpi." (PMID 41375455, 2025). "Prior to infection, animals that had been stimulated with live dpB (group 3) had higher IFN-γ, IL1-β TNF-α and IL-6 values than the group of inactivated dpB stimulated animals (group 1) or the infection controls (that had not been stimulated) (group 5)." (PMID 40969767, 2025). "The absence of Th-1 cytokines was corroborated by the complete absence of IFN-γ and low levels of TNFα in the infection milieu." (PMID 40586608, 2025). "Limitations of our study include the absence of baseline pre-infection OCTs, unavailability of serum biomarkers (e.g., IL-6, TNF-α), and lack of a defined post-infection imaging window." (PMID 40790570, 2025). "Pro-inflammatory cytokines and chemokines, including TNF-α, CSF3 and CCL4, were upregulated in both infection groups, alongside genes involved in immune cell adhesion and inflammatory responses (SELE), as well as stress response mediators such as HSP70 and PNLIPRP3." (PMID 41435987, 2025). "This pattern was also displayed upon infection with Lm, where again caspase activity was only statistically significantly reduced in CASP3−/− and CASP7−/− cells; this was particularly obvious in host cells that were simultaneously treated with TNF-α." (PMID 39885151, 2025). "IL-4, IL-10, and TNF-α levels were below the detection limit in all experimental conditions, regardless of infection status (data not shown)." (PMID 41415569, 2025). "Several studies have highlighted that M. stadtmanae can activate human dendritic cells, triggering the release of pro-inflammatory cytokines such as TNF-α and IL-6, suggesting potential immunopathogenic effects even in the absence of overt infection." (PMID 41305349, 2025). "Circulating levels of TNF-α, IL-1β, and IL-17a were elevated in mice infected with fas2Δ/Δ at 24 h post-infection compared to WT, whereas IFN-γ and IL-6 levels were significantly decreased but comparable to the saline (mock infection) control." (PMID 40138332, 2025). "TNF-induced lethal SIRS is characterized by hypothermia, hypotension, tissue damage, multiple organ failure and significant metabolic reprogramming, which is similarly observed in human patients following surgery, trauma, infection, burns or pancreatitis." (PMID 41132685, 2025). "Our results suggest that immune responses to injury in the context of NF-kB inhibition will over-activate TNFα, but will not induce a classic inflammatory profile, with implications for wound healing and clearing infection." (PMID 40461478, 2025). "For instance, it may inhibit the release of proinflammatory cytokines such as Tumor Necrosis Factor-alpha (TNF-α), Interleukin- beta (IL- β), and Interleukin-6 (IL-6), which are known to promote hormonal disruption and tissue damage during infection." (PMID 41400854, 2025). "Circulating levels of IL-6 were higher in acute and chronic phases compared to a group submitted to the MFD but not infected, while TNF-α showed a significant increase exclusively during the early infection." (PMID 40333112, 2025). "Serum levels of IL-10, IL-2, IL-6, IL-8, and TNF-α were analyzed and compared between patients with and without HAdV-36 infection." (PMID 40284995, 2025).
infection (continued). "In addition, to assess the expression of inflammatory factors during the infection of Ras264.7 macrophages with WT BCG, BCG::ΔmfpA, pMV361-mfpA/BCG::ΔmfpA, and pMV261-mfpA::BCG, we measured the levels of TNF-α and IL-6 in the cell culture supernatants." (PMID 40558494, 2025). "Previous studies have demonstrated that TNF-α can stimulate endothelial cells to express adhesion molecules like VCAM-1 and ICAM-1 (Intercellular adhesion molecule-1), which are key to promoting inflammation during infection." (PMID 40431657, 2025). "However, during the acute phase of infection, CX3CL1 receptor blockade increased TNF and IL-6 production in skeletal muscle." (PMID 40936920, 2025). "BMDC infection with M.tb CDC1551, measured TNF-α and IL-6 levels, and CD4+/CD8+ T cells in MLNS." (PMID 41256867, 2025). "In the present work, the plasma TNF-alpha concentration was significantly higher in group L than group H, though no obvious infections were observed in the sows." (PMID 41295269, 2025). "Both compounds also significantly reduced IL-6, IL-8, and TNFα release by hMDM in both infection models, regardless of differences between ATCC 33277 and W83 Pg strains." (PMID 41221328, 2025). "Infection with T. gondii activates inflammatory molecules—Interferon gamma (IFN-γ), Interleukin-2 (IL-2), and Tumor necrosis factor alpha (TNF-α)—which upregulate tryptophan-2,3-dioxygenase (TDO) and indoleamine-2,3-dioxygenase (IDO) while leading to degradation of tryptophan into kynurenine." (PMID 40868805, 2025). "Meanwhile, the accumulated AEGs in the vacuole are transported out of the fungus by EVs, where they act as a ligand for Mincle, promoting the production of cytokines such as TNF-α and MIP-2, which contributes to the clearance of KO strain at an early stage of infection." (PMID 40273119, 2025). "At 48 h post-infection, the supernatant of U937 macrophages infected with LRV-1+ isolates contained significantly higher concentrations of TNF-α (p < 0.01) and IL-1β (p < 0.0001), but a lower concentration of IFN-γ (p < 0.01), compared to macrophages infected with LRV-1− isolates." (PMID 41471220, 2025). "Indeed, intra-peritoneal EV-A71 infection at an early age of 14 days led to innate immune training of macrophages, which released more CCL17, IL-6, and tumor necrosis factor (TNF)." (PMID 39996724, 2025). "While WT infection also elevated TNF-α and IP-10 levels, PM pre-exposure did not result in a significant change, suggesting strain-specific differences in PM-mediated host epithelial responses." (PMID 41561095, 2025). "There was robust upregulation of proinflammatory cytokine genes (TNF–α, IL–1β, and IL–6) and chemokine genes (RANTES, MIP–1α, and MIP–1β), reflecting a strong inflammatory response that recruits immune cells to the site of infection." (PMID 41214723, 2025). "In the current study, TNF-α, IL-8, and IL-10 showed no clear pattern or increase after infection in the ORFV and CvHV2 infection trials, except for an increase in IL-8 levels at day 10 p.i. in animals infected with CvHV2." (PMID 40533814, 2025). "At the sites of infection, an increased number of CD8+ T cells, along with heightened expression of pro-inflammatory cytokines, e.g., Il-6 and TNFα, may have contributed to tissue damage." (PMID 41150440, 2025). "The low correlations were influenced by Asp infection (lime green star) showing distinctly higher levels for IL‐21 and IL‐22 compared to other types of infection, and MRSA infection (red square) showing distinctly higher levels of TNFα as compared to other infection types." (PMID 40031928, 2025). "Given that infection or inflammation could tip the Th1/Th2 balance toward a Th1-dominant cytokine milieu with elevated levels of IFN-γ and TNF-α, we sought to determine whether this could jeopardize mammary gland development and lead to lactation failure." (PMID 40564173, 2025).